SIRT1 (sirtuin 1)
Diseases named in the same sentence as SIRT1 in open-access papers (continued):
Sharing a sentence is not in itself a finding about the gene and the disease.
Obesity (continued). "Thus, AMPK/SIRT1 is a likely therapeutic target for obesity and its metabolic effects." (PMID 37509819, 2023). "In addition, it is unclear whether CR may decrease obesity via NF-κB inhibition through the AMPK/SIRT1 pathway." (PMID 35721807, 2022). "Additionally, we observed that miR-122 inhibition had a stronger effect in the sWAT, resulting in upregulation of direct target genes with beneficial effects on obesity—including Vav1, whose knockout displayed increased fat content by decreasing Sirt1 activity; or Ntrk3, which promotes browning." (PMID 36499248, 2022). "Moreover, the significantly better TBS of underweight patients compared to patients with obesity could be interpreted as more evidence in support of the beneficial effect of high SIRT1 and low sclerostin pattern on bone microarchitecture and quality." (PMID 35267956, 2022). "Many molecules and signaling pathways are involved in the pathogenesis of obesity, such as nuclear factor (NF)-κB, Toll-like receptors (TLRs), adhesion molecules, G protein-coupled receptors (GPCRs), programmed cell death 1 (PD-1)/programmed death-ligand 1 (PD-L1), and sirtuin 1 (SIRT1)." (PMID 36141228, 2022). "Notably, SIRT1 plays an important role in its protective effects against hyperglycemia or obesity." (PMID 35883777, 2022). "Interestingly, Sirt1 is modulated in states of increased CVD risk such as aging and obesity." (PMID 35561022, 2022). "Furthermore, epicatechin reduces the rate of weight gain by regulating mitochondrial genesis-related proteins (Sirt-1, PGC1a), suggesting that the supplementation of rutin or epicatechin could help avoid high-fat diet-induced obesity in mice." (PMID 36076880, 2022). "We have noted that AMPK negatively regulates lipid-induced inflammation, which acts through SIRT1, thereby contributing to the protection against obesity, inflammation, and insulin resistance, and the activation of both AMPK and SIRT1 may contribute to its anti-inflammatory effects." (PMID 34576066, 2021). "Therefore, it is unlikely that low levels of SIRT1 during obesity are functional." (PMID 33806509, 2021). "Furthermore, they also showed that FGF19 was able to protect the skeletal muscle against obesity-induced muscle atrophy through the AMP-activated protein kinase (AMPK)-Sirtuin-1 (SIRT1)-PGC1α pathway, which may be a potential target for obesity treatment." (PMID 34572066, 2021). "Therefore, we hypothesized that Ac may prevent against development of obesity by regulating lipid metabolism through activation of SIRT1 in visceral adipose tissue." (PMID 34578872, 2021). "Furthermore, it is reported that obesity-induced elevated miRNA-34a could suppress sirtuin 1 (SIRT1) function and adipocyte FGF21, while downregulation of miRNA-34a could improve hepatic FGF21 signaling to alleviate adiposity." (PMID 34349728, 2021). "Moreover, adipose-specific knockout of SIRT1 in mice results in obesity and insulin resistance." (PMID 33806509, 2021). "Taken together, Sirt1 activity within the hypothalamus is critical for the control of energy homeostasis and reproduction and the maintenance of its biological activity may be functional to prevent obesity and reproductive dysfunction." (PMID 33573212, 2021). "Given that miR‐22 directly targets genes such as Pgc‐1α, PPARα, and Sirt1, which are involved in the control of metabolism and obesity, it would be highly valuable to investigate whether miR‐22 may contribute to metabolic alterations induced by obesity." (PMID 33159388, 2021). "Also, α-mangostin treatment upregulated liver AMPK, SIRT-1 and PPARγ showing that this compound could ameliorate obesity and liver steatosis by these pathways." (PMID 33499382, 2021).
Obesity (continued). "With regard to genetic animal models for SIRT1, the global knock out (KO) mice for SIRT1 are not viable or have several metabolic complications, whereas moderate overexpression of SIRT1 in mice improves several metabolic parameters associated with obesity." (PMID 33572672, 2021). "Thus, we suggest that the favorable mechanism of CE on obesity and associated inflammation might be through the improvement of muscle mitochondrial biogenesis and function with AMPK/SIRT1 activation." (PMID 34684660, 2021). "This may be because prenatal HF diet, unlike prenatal HF diet or maternal obesity combined with postnatal HF diet, may not notably decrease SIRT1 expression in the offspring." (PMID 32316577, 2020). "Activation of SIRT1 that was shown to be involved in well-known signal pathways of diabetic cardiomyopathy has a protective effect against oxidative stress, inflammatory processes, and apoptosis that are the basis of diseases such as obesity, diabetes mellitus, or cardiovascular diseases." (PMID 32486051, 2020). "Therefore, the antioxidant effect of verbascoside could be regulated by increasing SIRT1 activity, leading to treatment of obesity and related metabolic disorders through AMPK activation." (PMID 32013273, 2020). "Likewise, mice lacking SIRT1 in VMH SF1 neurons are more susceptible to HFD-induced obesity and type 2 diabetes mellitus, whereas the mutant mice on an RCD display a normal body weight." (PMID 32143417, 2020). "Likewise, one may expect that down-regulation of Sirt1 would induce tubular damage in states of obesity." (PMID 32708636, 2020). "Additionally, increased expression and restored deacylase activity of Sirt-1 induced by CR could also explain the reduction of hepatic microsteatosis and obesity induced by transient postnatal OF." (PMID 31744052, 2019). "In addition to adiposity itself, high caloric diet leading to obesity may increase the CKD risk, through the circuitous loop among Sirt1, adiponectin, and podocyte effacement." (PMID 31770376, 2019). "Interestingly, several miRNAs such as miR-9, miR-181a, and miR-132, are capable of regulating insulin pathways through sirtuin 1 (SIRT1), a nicotinamide adenosine dinucleotide (NAD) that regulates energy homeostasis, inflammation, and metabolic disease associated with obesity." (PMID 31817583, 2019). "Furthermore, dysregulation of SIRT1 mediates obesity-induced memory impairments." (PMID 30416425, 2018). "The lack of SIRT1 in the SF1 neurons predisposed mice to dietary-induced obesity." (PMID 30532738, 2018). "In the light of this information, we reviewed recent findings related to the association of the increasing level of SIRT1 protein rather than reduction of the SIRT1 expression and regulation of some disease related conditions such as obesity, cardiovascular diseases and neurodegeneration." (PMID 30374331, 2018). "However, the cause-effect relationship cannot be established on the basis of our data and it is also possible that lower AT SIRT1 expression in obesity may be an effect of hyperinsulinemia." (PMID 29417372, 2018). "In addition, our findings raise the new possibility that vitamin D-mediated AMPK/SIRT1 activity could be a target for obesity prevention or treatment." (PMID 28353634, 2017). "However, involvement of microRNAs (miRNAs) in regulating SIRT1 during obesity-induced inflammation and insulin-resistance remains unclear." (PMID 29050301, 2017). "Therefore, activation of Sirt1 during adipogenesis could be beneficial in the therapeutic intervention of obesity." (PMID 27669202, 2016). "Our present study suggests that SRT1720 treatment may promote the ovarian lifespan of HF diet-induced obesity female mice by suppressing the activation of primordial follicles, the follicle maturation and atresia via activating SIRT1 signaling and suppressing mTOR signaling." (PMID 25330910, 2014).
Obesity (continued). "In this study, we generated conditional Sirt1 KI mouse models and asked whether conditional Sirt1 overexpression in mouse POMC or AgRP neurons prevents age-associated weight gain and diet-induced obesity." (PMID 24374551, 2014). "Moreover, low SIRT1 levels were correlated with insulin resistance and obesity." (PMID 25360511, 2014). "Therefore, the miR-146b/SIRT1 pathway could be a potential target for obesity prevention and treatment." (PMID 24009212, 2013). "Akt2 and Sirt1 therefore may be involved in formation of porcine obesity." (PMID 23951196, 2013). "Since peripheral blood leukocytes SIRT1 mRNA level was increase before total cholesterol and glucose level is increase, SIRT1 may become a candidate marker for early diagnosis of metabolic diseases including obesity in cats." (PMID 24073959, 2013). "Our studies and others have demonstrate that small molecule activators of SIRT1 or AMPK, such as resveratrol, the synthetic polyphenol S17834, and metformin, reduce the risk of hyperlipidemia for developing cardiovascular complications of obesity and type 2 diabetes." (PMID 23825667, 2013). "And we could not detect associations between genotype/haplotype of the SIRT1 gene and diabetes and obesity-related phenotypes including serum glucose levels, HbA1c, and BMI in this study." (PMID 23305113, 2013). "Interestingly, the beneficial effects of AICAR on adipose inflammation and insulin sensitivity were absent in MSKO mice fed HF diets, suggesting that the full capacity of AICAR to antagonize obesity-induced inflammation and insulin resistance requires myeloid SIRT1." (PMID 23183898, 2012). "Thus, increased SIRT1 activity appears to be anti-inflammatory in mice and resveratrol may improve obesity-induced inflammation and add to the potential of this dietary polyphenol in the control of obesity." (PMID 22115311, 2011). "Lack of SIRT1 in pro-opiomelanocortin (POMC) neurons causes hypersensitivity to HF obesity." (PMID 22115311, 2011). "Epicatechin decreases the rate of weight gain via increasing the expression of PGC-1α, UCP1, and SIRT1 and 3 involved in mitochondrial energy expenditure in a rat model of HFD-induced obesity." (PMID 40642166, 2025). "Resveratrol demonstrates protective effects against both acute and chronic kidney injuries in humans by its antioxidant properties and its ability to regulate Sirtuin 1 (SIRT1), a modulator of obesity." (PMID 40399974, 2025). "Given the established role of SIRT1 in mitochondrial biogenesis and the involvement of PPARγ/Lipin-1 in lipid handling, this pathway may contribute to the balance between lipid storage and oxidation, with potential implications for obesity, dyslipidemia, and insulin resistance." (PMID 41007632, 2025). "Additionally, genetic variation in SIRT1 might influence lung function and human longevity by modulating subclinical inflammation arising from abdominal adipose tissue, further underscoring its significance in the context of obesity and related diseases." (PMID 41011644, 2025). "Grape polyphenols inhibit proinflammatory pathways involved in obesity, for instance, MAPK, NF-κB and transcription factor AP-1, and stimulate anti-inflammatory transcription factors as SIRT1 and PPAR, and also increase histone deacetylase activity." (PMID 40642166, 2025). "Upregulation of SIRT1 has been shown to activate PGC-1α and FOXO1 through deacetylation, thereby alleviating mitochondrial dysfunction, insulin resistance, and obesity in mice fed a high-fat diet." (PMID 41228560, 2025). "MiR-34a, whose expression progressively increases with diet-induced obesity, enhances NF-κB activity by suppressing SIRT1 (sirtuin 1), a known inhibitor of NF-κB transcriptional output." (PMID 41463063, 2025). "In an obese mouse model (high-fat diet-induced obesity), obesity activates DNMTs through the cAMP/PKA/CREB pathway, leading to hypermethylation of oocytes and decreasing SIRT1 expression." (PMID 40620015, 2025).
Obesity (continued). "AMPK activation reduces macrophage infiltration and inflammation in adipose tissue and enhances SIRT1 activity by increasing the NAD+/NADH ratio, thereby preventing diet-induced inflammation and obesity-related metabolic dysfunction." (PMID 41194880, 2025). "SIRT1 overexpression has also been documented to significantly decrease the hyperacetylation of SIRT3 and enhance the activity of SIRT3 in obesity and aging-related diseases." (PMID 38767771, 2024). "Nonetheless, caloric restriction is effective in ameliorating obesity-related metabolic impairments and increasing mitochondrial biogenesis markers, primarily through metabolic pathways involving AMPK and SIRT1." (PMID 38976215, 2024). "In skeletal muscle, PGC-1α regulates muscle fiber type, averts muscle atrophy and regenerates muscle damage in obesity by activating AMPK and SIRT1." (PMID 39728000, 2024). "In summary, these data shows that the effects of SIRT1 levels on BMDC phenotype correlated with IDO1 and an active KYN pathway, which are both affected in obesity." (PMID 39424786, 2024). "Low SIRT1 levels correlate with increased fat deposition, vascular inflammation, LDL elevation, and obesity, while SIRT1 activation ameliorates insulin resistance, a reversible cause of vascular aging." (PMID 39598406, 2024). "SIRT1 serum levels were higher in LDs than normal weight subjects (mean ± SEM 4.18 ± 0.48 vs. 2.59 ± 0.20 ng/mL) and subjects with obesity (1.7 ± 0.39 ng/mL), whereas they were close to those measured in anorexia nervosa (3.44 ± 0.46 ng/mL)." (PMID 38732001, 2024). "Nevertheless, the correlations found between SIRT1 and IGFBP3 and between SIRT1 and tumor stage in obese CRC patients bolster its possible role in the progression of obesity-related CRC." (PMID 38704452, 2024). "SIRT-1 expression in adipose tissue and circulating BMDM is significantly suppressed in human obesity, contributing to an increased release of AT-derived exosomes." (PMID 39063184, 2024). "However, the impact of obesity on SIRT1 in dendritic cells (DCs) remains unknown." (PMID 39424786, 2024). "These levels are accompanied by significant decreases in the expression of genes related to mitochondrial biogenesis (Nrf, Tfam, Pgc1α, and Sirt1), fatty acid oxidation, and ETC complex subunits, indicating the effect of obesity on mitochondrial function." (PMID 38976215, 2024). "For example, sea buckthorn is found to reverse obesity induced by a high‐fat diet and promote fat browning through the activation of AMPK/SIRT1 pathway." (PMID 39055214, 2024). "We thus reveal a novel ACSS2 function in coupling PPARγ activation with degradation via SIRT1 and suggest D-mannose as a novel adipose plasticity regulator via ACSS2 to prevent obesity." (PMID 38332049, 2024). "In patients with obesity or NAFLD, SIRT1 levels are significantly reduced in the plasma and in the liver." (PMID 37894893, 2023). "SIRT-1 is related to NAD+ levels, which are known to decrease with age, hypertension, obesity, and diabetes." (PMID 37949890, 2023). "have an anti-adiposity effect, ameliorate obesity in HFD-induced obesity model and can alleviate obesity by regulating gut microbiota-mediated AMPK and NF-κB activation and SIRT-1 expression." (PMID 35767074, 2022). "Alterations in SIRT1 activity and NAD+ metabolism are frequently observed in acute and chronic kidney diseases of diverse origins, including obesity and diabetes." (PMID 35277012, 2022). "Overall, these findings suggest that high expression of SIRT1 and SIRT3 and low expression of SIRT2 and SIRT6 produced a metabolic state that inhibited the development of obesity, thereby reducing the occurrence of obesity." (PMID 36581622, 2022). "SIRT1, 3, 6, and NAD+ are involved in the regulation of dyslipidemia, while SIRT1, 3, 4, and 6 are involved in the prevention of obesity." (PMID 36361416, 2022). "Sirtuin 1 (SIRT1), an NAD+‐dependent class III histone deacetylase, is involved in aging, obesity, and metabolic diseases." (PMID 34826187, 2022).
Obesity (continued). "We aim to explore the anti-obesity effects of short-term moderate CR by improving energy metabolism via the SIRT1/AMPK pathway in white adipocytes and liver in a mouse model of obesity." (PMID 35721807, 2022). "Short-term moderate CR decreases obesity, increases the thermogenesis, and inhibits inflammation in a mouse model of obesity, probably via the activation of the AMPK/SIRT1 pathway in WAT and liver." (PMID 35721807, 2022). "Collectively, the SIRT1-PGC-1α-UCP1 axis explains the GABA and FCLL-GABA induced anti-obesity mechanism." (PMID 35458241, 2022). "Of note, SIRT1 and SIRT2 exert a dual effect on the progression of DM, while SIRT6 overexpression exacerbates diet-induced obesity." (PMID 36581622, 2022). "Evidence shows that RES can mediate obesity by inhibiting the activity of NF-κB and suppressing TNF-α through nicotinamide adenine dinucleotide (NAD)-dependent protein deacetylase sirtuin-1 (SIRT1) activation." (PMID 35164043, 2022). "SIRT1 is a well-characterized metabolic modulator, which is activated to ameliorate HFD-induced obesity." (PMID 35721807, 2022). "SIRT-1 is among the most studied sirtuins from class III histone deacetylases, which activation improves obesity related insulin resistance and possesses anti-inflammatory potential." (PMID 34834808, 2021). "MiR-34 suppresses WAT browning in obesity, by targeting Fibroblast Growth Factor Receptor 19 (FGFR19) and SIRT1 (sirtuin 1)." (PMID 34199293, 2021). "In spite of these somewhat contradictory results, we believe that SIRT1 and SIRT6 emerge as important targets for the development of novel therapies in the control of obesity and its comorbidities." (PMID 33572672, 2021). "Several studies have reported that caloric restriction induces the expression of the SIRT1 and SIRT3 and that obesity can reduce the expression of SIRT1 in humans." (PMID 33593418, 2021). "Metformin, an inhibitor of mTOR, can protect SIRT1 activity to maintain proper circadian rhythm of CLOCK and BMAL1 during obesity." (PMID 34356626, 2021). "It is well-documented that the protective effect of exogenous FGF21 on obesity and T2DM is closely depends on the activation of SIRT1 and subsequently leads to the deacetylation of its downstream targets, PGC-1α and H3 in human adipocytes." (PMID 34349728, 2021). "Evidence from other studies suggests that miR-34a directly targets and downregulates Sirtuin1 (SIRT1), an NAD + -dependent deacetylase, known to be protective against obesity." (PMID 34690698, 2021). "RES is known as an activator of Sirtuin 1 (SIRT1), a NAD+-dependent histone deacetylase contributing to oxidative stress, aging, metabolism, obesity, and tumors, as well as to DNA methylation." (PMID 34578972, 2021). "Obesity is further accompanied by reduction in phosphorylated SIRT‐1 in skeletal muscle, phosphorylated SIRT‐1, and AMPKα in liver." (PMID 33747489, 2021). "The major regulators of mitochondrial biogenesis and oxidative metabolism include SIRT1, PGC-1α, and TFAM which have been involved in the development of obesity-mediated IR." (PMID 34889901, 2021). "Some previous studies have suggested that AMPK, SIRT‐1 and PGC‐1α activity can be inhibited by obesity and other metabolic disorders, which impairs lipid and glucose metabolism in skeletal muscle." (PMID 33751819, 2021). "It is worth studying the SIRT1-involved signaling pathway and the interaction between AMPK in obesity and inflammation." (PMID 34576066, 2021). "TP63 knockout mice showed insulin resistance, obesity, and glucose intolerance; TP63 prevented these symptoms by increasing fatty acid synthesis and reducing fatty acid oxidation through the SIRT1/AMPKα2/LKB1 pathway." (PMID 33906607, 2021). "We recorded a high R2 coefficient of SIRT1 and adiponectin with the cardiac visceral EFT in the group of patients with obesity." (PMID 33202604, 2020). "HO-1 interacts with various pathways, such as sirtuin-1 (SIRT1) and PGC1α, to improve cell function in obesity." (PMID 32751794, 2020).